CDC37 (cell division cycle 37, HSP90 cochaperone)
Diseases named in the same sentence as CDC37 in open-access papers (continued):
Sharing a sentence is not in itself a finding about the gene and the disease.
infection (5 papers, 2015 to 2025). The state of being infected such as from the introduction of a foreign agent such as serum, vaccine, antigenic substance or organism. "Depletion of TRIM28 and CDC37 led to mitigated phosphorylation of IKKα/IKKβ within 30-120 min of infection." (PMID 29581850, 2018). "In 3D4/21 cells, with increasing NS5A infection time, the protein expression of AKT1, IKBKG, CDC37, MAP3K2, and PKN2 decreased, whereas the protein expression of KRAS2 and MAP3K7 increased." (PMID 40078537, 2025). "With increasing infection time, the expression levels of IKBKG and KRAS2 increased, whereas the expression levels of MAP3K7, MAP3K2, AKT1, CDC37, and PKN2 decreased." (PMID 40078537, 2025). "The results revealed that with increasing infection time, the expression of IKBKG, AKT1, CDC37, MAP3K2, and PKN2 decreased, whereas the expression of MAP3K7 and KRAS2 increased." (PMID 40078537, 2025). "The total amounts of TRIMs, STOML2, CDC37, PCBPs, DDX3 and PPP1C isoforms were unchanged in AGS cells within 9 h of infection." (PMID 29581850, 2018). "Importantly, ERC1, CDC37, WDR61 and TIPRL showed similar reduction in protein levels during infection with the AD169 virus." (PMID 26599541, 2015). "Here, we demonstrated that the RABV non-kinase P is chaperoned by Cdc37 and Hsp90 during infection." (PMID 27251758, 2016).
neurodegenerative disease (1 paper, 2019). A disorder of the central nervous system characterized by gradual and progressive loss of neural tissue and neurologic function. "Overall, Hsp90 and Cdc37 regulates many neurodegenerative disease-linked proteins." (PMID 31824256, 2019). "Thus, the Hsp90/Cdc37 complex may represent a potential drug target for regulating proteins linked to neurodegenerative diseases, through both direct and indirect interactions." (PMID 31824256, 2019). "Herein, we discuss the broad understanding of many Hsp90/Cdc37 pathways and how this protein complex may be a useful target to regulate the progression of neurodegenerative disease." (PMID 31824256, 2019).
neurological disorders (1 paper, 2024). "It has also been reported that overexpression of Cdc37 stabilizes tau and reduces its clearance, and pathological aggregates of tau have been found in many neurological diseases, including sporadic PD." (PMID 39273702, 2024).
prostate (1 paper, 2019). "Cell division control 37 (CDC37) increases the stability of heat shock protein 90 (HSP90) client proteins and is thus essential for numerous intracellular oncogenic signaling pathways, playing a key role in prostate oncogenesis." (PMID 31181782, 2019).
CDC37 also shares sentences with these, for which no sentence is quoted: lung carcinoma (4 papers); adenocarcinoma (1); anaplastic large cell lymphoma (1); atherosclerosis (1); autoimmune disease (1); clear cell renal cell carcinoma (1); diffuse large B-cell lymphoma (1); Ewing sarcoma (1); fibrosarcoma (1); fungal infections (1); gastrointestinal stromal tumor (1); Huntington disease (1); hyperglycaemia (1); leukemia (1); Parkinson disease (1); prostate tumor (1); T-cell lymphoma (1); tongue cancer (1); triple-negative breast carcinoma (1).